RALY (RALY heterogeneous nuclear ribonucleoprotein)
Description:
RNA-binding protein that acts as a transcriptional cofactor for cholesterol biosynthetic genes in the liver. Binds the lipid-responsive non-coding RNA LeXis and is required for LeXis-mediated effect on cholesterogenesis (By similarity). May be a heterogeneous nuclear ribonucleoprotein (hnRNP).
Synonyms: HNRPCL2; P542
Tractability: PROTAC: UniProt records ubiquitination sites on it; ubiquitination databases record sites on it; its protein half-life has been measured.
Gene: Protein-coding gene on chromosome 20 (33,993,632 to 34,108,308, forward strand). Ensembl gene ENSG00000125970.
Subcellular location: Nucleus
Subcellular location (Human Protein Atlas): Nucleoplasm; Vesicles
Gene Ontology:
Molecular function: protein binding; RNA binding; transcription coregulator activity; nucleic acid binding
Biological process: cholesterol homeostasis; mRNA splicing, via spliceosome; negative regulation of transcription by RNA polymerase II
Cellular component: catalytic step 2 spliceosome; nucleoplasm; nucleus
Genetic constraint (gnomAD): Loss-of-function variants: 15 observed, 31.48 expected, observed/expected ratio (o/e) 0.48, 90% interval 0.32 to 0.73. The upper end of that interval is the gene's LOEUF score, 0.73, which puts it in group 3 of 6, group 1 being the genes least tolerant of losing a copy. Missense variants: 339 observed, 420.56 expected, observed/expected ratio (o/e) 0.81, 90% interval 0.74 to 0.88. Synonymous variants: 177 observed, 174.05 expected, observed/expected ratio (o/e) 1.02, 90% interval 0.9 to 1.15.
Homologues: Orthologues: chimpanzee RALY (99% identical), macaque RALY (93% identical), rabbit RALY (89% identical), guinea pig RALY (88% identical), mouse Raly (87% identical), pig RALY (87% identical), rat Raly (80% identical), dog RALY (77% identical), tropical clawed frog raly (61% identical), zebrafish raly (61% identical). Paralogues in human: RALYL (53% identical), HNRNPC (44% identical), HNRNPCL1 (42% identical), HNRNPCL2 (41% identical), HNRNPCL3 (41% identical), HNRNPCL4 (41% identical).
Diseases named in the same sentence as RALY in open-access papers:
RALY is named in the same sentence as 37 diseases in open-access papers, as found by Europe PMC text mining. Sharing a sentence is not in itself a finding about the gene and the disease. The quoted sentences say what the papers report.
breast carcinoma (6 papers, 2011 to 2023). "Overexpression of RALY was associated with poor survival in ovarian, lung, bladder, brain, and breast cancers as well as in multiple myelomas and melanomas." (PMID 22118625, 2011). "Similar to the results of this study, in breast cancer cells, RALY expression is increased and negatively related to the patients’ survival period." (PMID 37906341, 2023). "Importantly, transcript of RALY is overexpressed in various cancer tissues, furthermore, overexpression of RALY involve poor outcome in ovarian, lung, bladder, brain, and breast cancers." (PMID 35941292, 2022). "In addition, RALY acted as a RNA binding protein to modulate metastatic potential of breast cancer cells." (PMID 31781561, 2019). "In fact, RALY primarily localizes in the nucleus and regulating transcription of many genes which involved in cell cycle and transcription regulation, as well as the alternative splicing of the pre-mRNA of PRMT1 and the metastasis of breast cancer cells." (PMID 35941292, 2022). "For example, RALY and SNW1 stimulate exon 2 inclusion in PRMT1, promoting breast cancer invasiveness and CDK12 promote alternative last exon splicing of DNA damage genes ATM and DNAJB6 thereby increasing migration and invasiveness of breast cancer cells." (PMID 31666932, 2019). "Interestingly, we also identified splice factors that have not been linked to other hallmarks in breast cancer before, such as CRNKL1, RALY and JUP." (PMID 31666932, 2019).
colorectal cancer (6 papers, 2011 to 2022). A primary or metastatic malignant neoplasm that affects the colon or rectum. "RALY (HNRNPCL2) is newly found as an RNA-binding protein associated with the aggressiveness of colorectal cancer (CRC)." (PMID 36553003, 2022). "Our results, however, indicate that RALY is the only protein that sensitizes colorectal cancer cells to oxaliplatin when depleted with siRNAs." (PMID 22118625, 2011). "Knock down analyses of two of these proteins, NONO and RALY, increased oxaliplatin sensitivity in otherwise resistant colorectal cancer cells overexpressing YB-1." (PMID 22118625, 2011). "We show for the first time that YB-1 interacts with NONO and RALY in the colorectal cancer cell line SW480." (PMID 22118625, 2011). "Independent of the exact mechanisms involved in oxaliplatin resistance, NONO and RALY are good potential targets for the sensitization of otherwise oxaliplatin resistant YB-1 overexpressing colorectal cancer tumor cells." (PMID 22118625, 2011). "Interestingly, down-regulation of RALY expression sensitizes cell lines of colorectal cancer treated with oxaliplatin without effect on the rate of cell growth, indicating the chemotherapeutic role of RALY." (PMID 35941292, 2022). "Epidemiological studies on appropriate cohorts of patients with colorectal cancer are warranted to determine whether the expressions of YB-1, NONO, and RALY have predictive values for the response to oxaliplatin treatment." (PMID 22118625, 2011). "Importantly, the knock down of either NONO or RALY sensitizes in otherwise oxaliplatin overexpressing YB-1 SW480 and HT29 colorectal cancer cell lines." (PMID 22118625, 2011).
melanoma (5 papers, 2011 to 2021). A malignant, usually aggressive tumor composed of atypical, neoplastic melanocytes. "Based on human phenotype association evidence for RALY from the GWAS Catalog, we found mutations of this gene associated with melanoma, skin pigmentation, and skin sensitivity to sun." (PMID 31001324, 2019). "The ASIP region is one of four known melanoma-susceptibility regions and includes the four genes (RALY, EIF2S2, CHMP4B and ASIP)." (PMID 26083354, 2015). "The SNP rs6059655, intergenic near RALY-ASIP, is associated with facial pigmentation spots and rs35407 (SLC45A2), is associated with pigmentation and melanoma risk." (PMID 28212542, 2017). "The two newly discovered regulatory mutation blocks may contribute to the dysregulation of RALY and RPS27 and are worthy for further investigation because both genes are known to be significantly associated with melanoma." (PMID 31001324, 2019). "Knockdown of NONO/RALY complex components reversed YB-1 overexpression-induced oxaliplatin resistance in CRC cells, while NONO silencing modulated the cellular response to ultraviolet-induced DNA damage in melanoma cells." (PMID 33420374, 2021).
hepatocellular carcinoma (4 papers, 2019 to 2024). A malignant tumor that arises from hepatocytes. "The similar correlation between RALY overexpression and poor survival in hepatocellular carcinoma has also been reported." (PMID 35941292, 2022). "Recent study indicated that overexpression of RALY predicted poor prognosis and acted as an oncogene in hepatocellular carcinoma." (PMID 31781561, 2019). "RALY, another RNA binding protein, could activate the cholesterol synthesis in hepatocellular carcinoma." (PMID 37962768, 2023). "Another study showed that decreasing the expression of RALY inhibits cell proliferation and against aggressive biological behavior in hepatocellular carcinoma cells (HCC)." (PMID 35941292, 2022).
skin cancer (3 papers, 2019 to 2022). "RALY is differentially expressed between the skin cancer patients and the normal control samples." (PMID 31001324, 2019). "BNC2, HERC2, OCA2, RALY, and TYR are pleiotropic for Category B Phenotypes (skin colour phenotypes) and Category C Phenotypes (skin cancer phenotypes)." (PMID 35907981, 2022).
viral infection (3 papers, 2022 to 2024). "To investigate the effects of PEDV infection on RALY expression, we analyzed the mRNA and protein levels of RALY during viral infection." (PMID 35753351, 2022). "However, no RPS16 and GAPDH bands were detected in the precipitated samples, indicating that RALY interacts with the FMDV RNA during viral infection." (PMID 38323828, 2024). "Here, we provide evidence for a novel mechanism of RALY-mediated viral infection control." (PMID 35753351, 2022). "Besides its role in viral infection, RALY also promotes cancer in multisystem tumors, promoting the proliferation of breast cancer, and promotes cancer in multisystem tumors, promoting the proliferation of breast, hepatocellular carcinoma, and cervical cancer cells." (PMID 38323828, 2024). "Some studies have shown that the ubiquitination of RALY and hnRNP-C mediated by Adenovirus (AD) removes the restriction on viral RNA processing and reveals the unexpected role of non-degradable ubiquitination in the manipulation of cellular processes during virus infection." (PMID 35464981, 2022). "The RALY polyubiquitylation in BHK-21 cell-infected FMDV was enhanced following viral infection, indicating that FMDV 3Cpro degraded RALY protein." (PMID 38323828, 2024).
colon adenocarcinoma (2 papers, 2011 to 2023). "The depletion of only two proteins, NONO and RALY, lead to a greater sensitivity to oxaliplatin in both colon adenocarcinoma cell lines with at least two siRNA sequence molecules." (PMID 22118625, 2011). "Moreover, YBX1 could induce oxaliplatin resistance in colon adenocarcinoma cell lines by induction of NONO and RALY proteins." (PMID 35861369, 2023).
glioma (2 papers, 2023 to 2025). A benign or malignant brain and spinal cord tumor that arises from glial cells (astrocytes, oligodendrocytes, ependymal cells). "This study demonstrated that RALY was modified by SUMO1 at the major conjugation site K175 in glioma cells." (PMID 37906341, 2023). "The increased UBA2 expression in glioma cells promoted RALY SUMOylation, which, in turn, upregulated the expression of RALY by increasing its stability." (PMID 37906341, 2023). "In the present study, we found that UBA2 and RALY were upregulated in glioma tissues and cell lines." (PMID 37906341, 2023). "According to the GEPIA database, glioma patients with high RALY expression were found to have a low overall survival rate." (PMID 37906341, 2023). "In our study, we aimed to clarify the molecular mechanism of SUMOylation of RALY in human glioma cells." (PMID 37906341, 2023). "This study revealed that the expression levels of UBA2 and RALY in glioma cells and tissues are significantly increased, and RALY can be modified by SUMO1 in glioma." (PMID 37906341, 2023). "Furthermore, the overexpression of RALY facilitated the migration, invasion, and vasculogenic mimicry of glioma cells and, more importantly, rescued the suppression of migration, invasion, and VM induced by UBA2 knockdown." (PMID 37906341, 2023). "Furthermore, overexpression of FOXD1 rescued the suppression of migration, invasion, and VM induced by RALY knockdown in glioma cells." (PMID 37906341, 2023). "Inhibition of RALY hindered migration, invasion, and VM in glioma cells via FOXD1 destabilization." (PMID 37906341, 2023). "UBA2/RALY/FOXD1/DKK1 axis may play crucial roles in regulating VM in glioma, which may contribute to the development of potential strategies for the treatment of gliomas." (PMID 37906341, 2023). "Downregulation of UBA2 and RALY inhibited the migration, invasion, and VM of glioma cells." (PMID 37906341, 2023). "Moreover, the overexpression of FOXD1 rescued the suppression of migration, invasion, and VM induced by RALY knockdown in glioma cells." (PMID 37906341, 2023). "In this study, we found that the expression levels of UBA2, RALY, FOXD1, and DKK1 were significantly increased in glioma cells and tissues and were negatively correlated with the overall survival time in glioma patients." (PMID 37906341, 2023). "The combined inhibition of UBA2, RALY, and FOXD1 significantly impeded glioma cell migration, invasion, and VM compared with the control group." (PMID 37906341, 2023). "Interactions among UBA2, RALY, FOXD1, and DKK1 play an important role in regulating migration, invasion, and vasculogenic mimicry in glioma cells." (PMID 37906341, 2023). "In addition, SUMOylation by UBA2 is also operative in glioma: UBA2 and its target RALY are increased in glioma cells and UBA2 knockdown inhibits vasculogenic mimicry and glioma cell proliferation." (PMID 41300918, 2025). "Similarly, in our study, the immunofluorescence analysis showed that RALY and SUMO1 are mainly colocalized in the nucleus of glioma cells." (PMID 37906341, 2023). "In addition, we profiled the expression of UBA2, RALY, FOXD1, and DKK1 and explored the probable interaction mechanism among these molecules in the regulation of vasculogenic mimicry (VM) in glioma." (PMID 37906341, 2023). "In addition, we found that the inhibition of UBA2, RALY, FOXD1, and DKK1 inhibited glioma cell migration, invasion, and vasculogenic mimicry." (PMID 37906341, 2023). "The inhibitor of UBA2, RALY, FOXD1, and DKK1 may serve as the therapeutic target in glioma." (PMID 37906341, 2023).
alopecia (1 paper, 2019). Hair loss usually from the scalp. "Although the SNP is not far from the RALY gene, it mapped within the EIF2S2 gene, which has been shown to be involved in protection against chemotherapy-induced alopecia." (PMID 31708969, 2019).
aortic atherosclerosis (1 paper, 2020). A atherosclerosis that involves the aorta. "LeXis interacted with the ribonuclear protein RALY to aid in transcription of cholesterol metabolism genes in the liver, and in vivo delivery of LeXis using an adenoviral vector reduced aortic atherosclerosis in mice." (PMID 33021969, 2020).
COVID-19 (1 paper, 2022). A disease caused by infection with severe acute respiratory syndrome coronavirus 2. "Of note, we observed numerous DTU genes involved in RNA splicing, with 10 genes (e.g. HNRNPC, SNRPD3, QKI, and LUC7L2) increased major transcript usage and 18 genes (e.g. SNRNP48, NCBP1, CELF2, RALY, and PABPC1) decreased major transcript usage in the COVID-19 patients." (PMID 35421082, 2022).
esophageal squamous cell carcinoma (1 paper, 2023). Esophageal squamous cell carcinoma (ESCC) is a type of esophageal carcinoma (EC) that can affect any part of the esophagus, but is usually located in the upper or middle third. "Moreover, in esophageal squamous cell carcinoma RALYL (RALY RNA Binding Protein-like) is targeted by miR-3912 to hinder transcriptional and post-transcriptional regulatory processes." (PMID 37310937, 2023).
gastric cancer (1 paper, 2026). A primary or metastatic malignant neoplasm involving the stomach. "This study reveals a novel mechanism wherein tRF-3005a promotes gastric cancer development by regulating RALY-mediated alternative splicing of SPAG4 to activate the GRB14/PI3K/AKT pathway, suggesting it may serve as a prognostic biomarker and therapeutic target." (PMID 41872130, 2026).
hypopharyngeal cancer (1 paper, 2020). Carcinoma, predominantly squamous cell, arising from the epithelial cells of the hypopharynx. "Moreover, Kaplan–Meier analysis indicated that high or low expression of genes, including RALY, TSTA3, and HLA-A, was associated with significant differences in survival in hypopharyngeal cancer and laryngeal cancer patients (p < 0.05)." (PMID 33173143, 2020).
Insulin resistance (1 paper, 2023). Increased resistance towards insulin, that is, diminished effectiveness of insulin in reducing blood glucose levels. "Interestingly, lethal yellow, a classic mouse model of obesity and insulin resistance, is characterized by a spontaneous mutation that leads to deletion of RALY and overexpression of the neighboring agouti gene." (PMID 37909330, 2023).
lymph node metastasis (1 paper, 2023). "In NSCLC, RALY expression is notably upregulated and associated with a higher incidence of lymph node metastasis and poorer patient survival." (PMID 37906341, 2023).
Non-Alcoholic Steatohepatitis (1 paper, 2020). "To more thoroughly investigate the contributions of RALY in chronic lipid abundance states, we fed L-RalyKO mice and controls a diet known to induce sterol accumulation and Non-Alcoholic Steatohepatitis (NASH)." (PMID 32080181, 2020).
oral cancer (1 paper, 2015). "In addition, our results also suggested interaction of hnRNPD with other RNA binding proteins (RBPs) such as ELAVL1, RALY, EWSR1 and FUS in oral cancer." (PMID 26318153, 2015).
ovarian carcinoma (1 paper, 2011). A malignant neoplasm originating from the surface ovarian epithelium. "Based on microarray studies of different cell lines, the proteins HNRPL, PABPC1, RPS4X, RPS7, and RALY are overexpressed in ovarian cancer cells resistant to oxaliplatin." (PMID 22118625, 2011).
phlebitis (1 paper, 2024). Inflammation of a vein. "Moreover, RALY was positively associated with the risk of phlebitis and thrombophlebitis (β = 2.36, p = 1.67e−05)." (PMID 39284832, 2024).
prostate carcinoma (1 paper, 2024). A carcinoma that arises from epithelial cells of the prostate gland. "Mechanistically, PTBP1 binds to RALY and together regulates alternative splicing of DNMT3B to increase DNMT3B‐L accumulation, leading to hypermethylation of the DUSP2 promoter and downregulation of its expression, and then increasing radioresistance of prostate cancer." (PMID 39287090, 2024).